CEBPA (CCAAT enhancer binding protein alpha)
Diseases named in the same sentence as CEBPA in open-access papers (continued):
Sharing a sentence is not in itself a finding about the gene and the disease.
colon cancer (8 papers, 2006 to 2023). "We have already confirmed that ASNS and CEBPA expression were associated with lymph node metastasis in colon cancer patients." (PMID 35174151, 2022). "The low expression of ASNS and CEBPA in colon cancer tissues was closely related to the occurrence of lymph node metastasis, which had an impact on prognosis and shortened OS (Freeman., 2013)." (PMID 35174151, 2022). "Therefore, it can be speculated that CREB antagonizes the effect of insulin in colon cancer, reduces the activation and expression of CEBPA, and play a carcinogenic role." (PMID 35174151, 2022). "In this study, three key genes, ASNS, CEBPA, and CAD, were screened by Cox regression analysis in colon cancer." (PMID 35174151, 2022). "It was found that in our cluster model, ASNS and CEBPA play an important role in the prognosis of colon cancer patients, and patients with low ASNS and CEBPA expression had a worse prognosis, i.e., more prone to lymph node metastasis." (PMID 35174151, 2022). "We further examined the expression of ASNS, CEBPA, and CAD in tumor tissues and adjacent normal tissues from different colon cancer patients." (PMID 35174151, 2022). "Based on the expression profiles of ASNS, CEBPA, and CAD, 415 TCGA colon cancer samples were analyzed by consistent clustering and tSNE algorithm, and the samples were divided into two clusters, Cluster 1 and Cluster 2, with longer and shorter survival time, respectively." (PMID 35174151, 2022).
colorectal cancer (8 papers, 2016 to 2024). A primary or metastatic malignant neoplasm that affects the colon or rectum. "Among them, MMP12 was highly expressed in colorectal cancer tissues, while ARMCX2, CEBPA, CXCL13, FABP4, HOXC6, SIGLEC1 and VSIG4 were more expressed in normal tissues than in cancer tissues." (PMID 36544770, 2022). "Because the expression of FOXA1 and CEBPA was not induced by the knockdown of β-catenin in colorectal cancer cells, transcription factors that are expressed in liver tissues might be involved in the regulation of CEBPA and/or FOXA1 expression." (PMID 38684876, 2024).
COVID-19 (7 papers, 2021 to 2025). A disease caused by infection with severe acute respiratory syndrome coronavirus 2. "Comparing the COVID-19-specific HEP7 cells to the closely related HEP6 cells, shows an inverse CEBPA/CEBPB ratio, demonstrating a metabolic vs. acute phase regulation expression program." (PMID 40087773, 2025).
glioblastoma (7 papers, 2011 to 2025). The most malignant astrocytic tumor (WHO grade IV). "We also found that the transcription factor CCAAT enhancer-binding protein alpha (CEBPA), located on chromosome 19q, played a key role in regulating the expression level of Galectin-9 in both lower-grade glioma (LGG) and glioblastoma (GBM)." (PMID 34956239, 2021).
liver diseases (7 papers, 2018 to 2024). "Until now, the pathological function of cell-specific CEBPA in influencing the progression of various liver diseases is still largely unexplored." (PMID 38557493, 2024). "Studies regarding the cell-specific roles of CEBPA in hepatocytes or other cells in liver diseases represent a promising research field to guide the discovery of CEBPA modulation–based gene therapy." (PMID 38557493, 2024). "Previous studies have suggested that CEBPα is a master transcription factor that reverses liver dysfunction across various liver disease models, including fibrosis, cirrhosis, and HCC." (PMID 34298689, 2021).
melanoma (7 papers, 2013 to 2025). A malignant, usually aggressive tumor composed of atypical, neoplastic melanocytes. "Another important key regulator is CEBPA, which is down-regulated in melanoma and up-regulated in BC, a key TF involved in the regulation of cellular processes, especially in Hematopoietic system." (PMID 25077705, 2014).
myelodysplastic syndrome (7 papers, 2014 to 2025). A clonal hematopoietic disorder characterized by dysplasia and ineffective hematopoiesis in one or more of the hematopoietic cell lines. "For instance, germline CEBPA and DDX41 mutations are related to the family predisposition to myelodysplastic syndrome (MDS) and AML." (PMID 35279121, 2022). "Molecular testing for FLT3, NPM1, and CEBPA was not performed, given the picture of antecedent myelodysplastic syndrome (MDS)." (PMID 26114018, 2014).
type 2 diabetes (7 papers, 2013 to 2024). "Our finding that CEBPA plays a direct role in controlling expression of genes that impinge on protein folding, ER stress, and the UPR suggests that it may be leveraged as a potential intervention to expand functional β-cell mass for patients with type 2 diabetes." (PMID 38392328, 2024).
viral infection (7 papers, 2014 to 2025). "Interestingly, there is no consensus as to how CCAAT/enhancer binding proteins (such as CEBPA) function in general during viral infection, but they have been previously implicated in promoting the replication of some viruses." (PMID 25079789, 2014). "Here, the authors show that mouse lung alveolar type 2 cells undergo maturation postnatally and their plasticity is restricted by CEBPA and increases upon viral infection." (PMID 38755149, 2024).
atherosclerosis (6 papers, 2014 to 2024). A disease characterized by the build-up of fatty material and calcium deposition in the arterial wall resulting in partial or complete occlusion of the arterial lumen. "CEBPA is upregulated in unstable plaques, and overexpression of CEBPA may contribute to the occurrence and development of atherosclerosis." (PMID 38097358, 2023).
bladder cancer (6 papers, 2014 to 2024). "For example, in bladder cancer (BLCA) we have provided a list of 65, 208, and 65 genes that may be regulated by POU3F1, FOXA1, or CEBPA, respectively, by binding to a specific hypomethylated enhancer." (PMID 25994056, 2015).
lung fibrosis (6 papers, 2018 to 2025). "Restoring CEBPA expression in lung organoids ex vivo and during experimental lung fibrosis in vivo rescued CEBPA deficiency–mediated phenotypes." (PMID 39012710, 2024). "By mining publicly available RNA-Seq data sets, we identified loss of CCAAT enhancer-binding protein alpha (CEBPA) as a candidate contributor to idiopathic pulmonary fibrosis (IPF)." (PMID 39012710, 2024). "We used conditional KO mice, scRNA-Seq, lung organoids, small-molecule inhibition, and potentially novel gene manipulation methods to investigate the role of CEBPA in lung fibrosis and repair." (PMID 39012710, 2024). "CEBPA deficiency causes loss of AT2 cells and induces profibrotic response, which provides new possibilities for lung fibrosis treatment by restoring insufficient CEBPA expression." (PMID 39012710, 2024). "Future research may uncover the epigenetic mechanism of CEBPA repression in human pulmonary fibrosis, potentially leading to additional strategies for restoring gene regulation." (PMID 39012710, 2024). "Based on evidence implicating fibroblast fate switching between lipogenic and myogenic states in lung fibrosis and resolution, and CEBPA in lipogenesis, we hypothesized that CEBPA expression in lung fibroblasts regulates the lipofibroblast phenotype." (PMID 31829168, 2019). "Our study establishes a direct mechanistic link between CEBPA repression, impaired AT2 cell identity, disrupted tissue homeostasis, and lung fibrosis." (PMID 39012710, 2024). "After establishing that CEBPA expression levels are consistently lower in the epithelial cells from human IPF versus control lung samples, we aimed to investigate Cebpa expression in an experimental lung fibrosis mice model." (PMID 39012710, 2024). "Notably, TH signaling has been shown to inhibit lung fibrosis in mice by improving epithelial mitochondrial function and enhancing alveolar cell differentiation through Kruppel-Like Factor 2 (KLF2) and CCAAT-enhancer binding protein alpha (CEBPA)." (PMID 40605078, 2025).
platelet disorder (6 papers, 2021 to 2025). "These rare disorders are characterized by either CEBPA or DDX41 mutations and are often inherited in families without a pre-existing platelet disorder or organ dysfunction." (PMID 38473358, 2024).
fibrosis (5 papers, 2021 to 2024). the formation of excess fibrous connective tissue in an organ or tissue in a reparative or reactive process. "The effect of hepatocyte-specific CEBPA overexpression in the treatment of MASH-associated fibrosis was next examined." (PMID 38557493, 2024).
injury (5 papers, 2019 to 2025). Damage inflicted on the body as the direct or indirect result of an external force, with or without disruption of structural continuity. "CEBPα promotes miR-223 expression to exert an effect in human granulopoiesis, and the CEBPα/miR-223 axis in neutrophils was further proven to reduce the susceptibility to alcohol-induced liver injury." (PMID 36747241, 2023).
neutropenia (5 papers, 2016 to 2024). A decrease in the number of neutrophils found in the blood. "Recent studies in mice clarified that HSPC depletion in CEBPA enhancer deletion mutants resulted from neutropenia due to continuous HSPC exhaustion by quiescence." (PMID 39500381, 2024). "Dysregulated expression and mutations of the CEBPA gene are associated with acute myelogenous leukemia (AML) and neutropenia." (PMID 39555410, 2024).
thyroid cancer (5 papers, 2020 to 2024). "Of note, CEBPA and DACH1 have been reported as tumour suppressors in different types of cancers, while their function in thyroid cancer is currently unknown." (PMID 38797942, 2024). "Thus, CEBPA and DACH1 could be direct target genes of miR‐31 during thyroid cancer development." (PMID 38797942, 2024).
myeloproliferative neoplasm (4 papers, 2017 to 2021). A clonal hematopoietic stem cell disorder, characterized by proliferation in the bone marrow of one or more of the myeloid (i.e., granulocytic, erythroid, megakaryocytic, and mast cell) lineages. "UPN09 was diagnosed with secondary AML (prior diagnosis of myeloproliferative neoplasm (MPN); AML not otherwise specified (NOS), AML without maturation, normal male karyotype, no BCR–ABL1 fusion, no CEBPA, FLT3, or NPM1 mutation) in 2008." (PMID 34950586, 2021).
osteoporosis (4 papers, 2018 to 2025). A condition of reduced bone mass, with decreased cortical thickness and a decrease in the number and size of the trabeculae of cancellous bone (but normal chemical composition), resulting in increased fracture incidence. "In this study, we found that the expression of miR-10b was positively correlated with bone formation marker genes ALP, RUNX2 and OPN, and negatively correlated with adipogenic markers CEBPα, PPARγ and AP2 in clinical osteoporosis samples." (PMID 30574418, 2018). "We collected 30 clinical samples from osteoporosis patients of different ages and analyzed the correlation between the expression of miR-10b and the bone formation marker genes ALP, OPN and RUNX2, and the correlation between miR-10b and adipocyte formation markers CEBPα, PPARγ and AP2." (PMID 30574418, 2018).
breast tumors (3 papers, 2020 to 2023). "Indeed, using the probes against these methylation sites, we confirmed that the methylation levels of CEBPA were markedly higher in breast tumors than in normal tissues." (PMID 38102722, 2023).
cervical carcinoma (3 papers, 2014 to 2025). A carcinoma arising from either the exocervical squamous epithelium or the endocervical glandular epithelium. "KCP can also act positively on the downstream gene SERPINB3 and negatively on the downstream gene CEBPA to participate in the proliferative function of cervical squamous carcinoma cells and affect the resistance of cervical carcinoma to paclitaxel." (PMID 40297811, 2025). "CEBPα mRNA level was significantly lower in cervical cancer tissues than in normal cervical tissues (P < 0.01)." (PMID 24913332, 2014). "Fifteen cervical carcinoma tissues and their corresponding normal cervical tissues were examined for CEBPα gene expression by real time quantitative RT-PCR." (PMID 24913332, 2014). "The average CEBPα mRNA level was 3.07 ± 1.04 in cervical cancer tissues and 5.63 ± 2.98 in their corresponding normal cervical tissues." (PMID 24913332, 2014). "Methylation of the promoter of CEBPα gene in CpG 5, CpG-14.15, CpG-19.20 were significantly higher in cervical cancer than in normal cervical tissues (P < 0.05, P < 0.01, P < 0.05, respectively)." (PMID 24913332, 2014). "We observed that KCP could act positively on the downstream gene SERPINB3 and negatively on the downstream gene CEBPA to affect the resistance of cervical carcinoma cells to paclitaxel." (PMID 40297811, 2025). "According to the IPA analysis of differentially expressed genes, qPCR was used to verify KCP could also act positively on the downstream gene of SERPINB3 and negatively on the downstream gene of CEBPA to affect the resistance of cervical carcinoma to paclitaxel." (PMID 40297811, 2025). "Thus, the expression of CEBPα gene was reduced significantly in cervical carcinoma tissues." (PMID 24913332, 2014).
diffuse large B-cell lymphoma (3 papers, 2013 to 2021). "In addition, it has been reported that CEBPA-regulated PER2 activation is a potential tumor suppressor pathway in diffuse large B-cell lymphoma (DLBCL)." (PMID 34178023, 2021).
endometriosis (3 papers, 2018 to 2024). The growth of functional endometrial tissue in anatomic sites outside the uterine body. "Additional defects in H3K27ac deposition in individuals with endometriosis were observed in the well-known progesterone-responsive genes RARB and CEBPA loci." (PMID 38402336, 2024). "The top five key regulators in the miRNA-TF-gene network of endometriosis were FOXC1, FOXO1, miR-182-5p, miR-106a-5p, and CEBPA, which were directly connected to 117, 64, 57, 49, and 49 corresponding targets, respectively." (PMID 29357938, 2018). "Specifically, some key regulators from the miR-449 and miR-34b/c cluster, miR-200 family, miR-106a-363 cluster, miR-182/183, FOX family, GATA family, and E2F family as well as CEBPA, SOX9 and HNF4A were suggested to play vital regulatory roles in the pathogenesis of endometriosis." (PMID 29357938, 2018). "This negative correlation between miR-182 and CEBPA is consistent with our result; however, their specific mechanism and involvement in the downstream signaling pathway in endometriosis need to be further confirmed." (PMID 29357938, 2018).
experimental autoimmune encephalomyelitis (3 papers, 2012 to 2023). An autoimmune demyelinating disease of the central nervous system that is produced experimentally in animals by the injection of homogenized brain or spinal cord in Freund's adjuvant. "During experimental autoimmune encephalomyelitis, miR-124 deactivated macrophages by targeting CEBPα." (PMID 36747241, 2023). "Chr 3: MIR124-2 host gene is the most abundant brain-specific miR, promotes microglial quiescence, inhibits microglial and astrocyte activation, and suppresses experimental autoimmune encephalomyelitis by deactivating macrophages via the CEBPA/C/EBP-a-SPI1/PU.1 pathway." (PMID 37987368, 2023).
head and neck squamous cell carcinoma (3 papers, 2016 to 2017). A squamous cell carcinoma that arises from any of the following anatomic sites: lip and oral cavity, nasal cavity, paranasal sinuses, pharynx, larynx, and salivary glands. "Down-regulation of CEBPA due to its promoter methylation was also reported in head and neck squamous cell carcinoma (HNSCC)." (PMID 27602952, 2016).
intracerebral hemorrhage (3 papers, 2020 to 2023). A cerebrovascular disorder characterized by bleeding into one or both cerebral hemispheres including the basal ganglia and the cerebral cortex. "In this study, we explored the possible roles of miR-367 and CEBPA in intracerebral hemorrhage (ICH)." (PMID 33150481, 2020).
pancreatic ductal adenocarcinoma (3 papers, 2012 to 2022). An infiltrating adenocarcinoma that arises from the epithelial cells of the pancreas. "Using NetRank, we identified seven genes (STAT3, FOS, JUN, SP1, CDX2, CEBPA, and BRCA1) as most relevant for predicting survival in patients with pancreatic ductal adenocarcinoma." (PMID 22615549, 2012). "Given the success of MTL-CEBPA in clinical trials for advanced HCC, the drug has attracted interest as a novel therapeutic agent in other cancers, such as pancreatic ductal adenocarcinoma, for which saRNA targeting CEBPA has been reported to have anti-tumour effects both in vitro and in vivo." (PMID 36700046, 2022).
periodontitis (3 papers, 2022 to 2023). An acute or chronic inflammatory process that affects the tissues that surround and support the teeth. "Deficiency of Ncor1 in macrophages exacerbates periodontitis by regulating Cebpα transcription through PPARγ, promoting osteoclastogenesis and neutrophil accumulation in mice with experimental periodontitis." (PMID 38030614, 2023). "In periodontitis, lower serum levels of CEBPA have been reported." (PMID 35132337, 2022).
preeclampsia (3 papers, 2014 to 2022). Preeclampsia is a hypertensive disorder of pregnancy that is characterized by new-onset hypertension with proteinuria presenting after 20 weeks of gestation, and depending on mild or severe forms may initially present with severe headache, visual disturbances, and hyperreflexia. "We developed a 5-mRNA signature (termed PE5-signature) to diagnose preeclampsia from 38 DEGs using recursive feature elimination with a random forest supervised classification algorithm, including ENG, KRT80, CEBPA, RDH13 and WASH9P." (PMID 35774506, 2022).
rotator cuff tears (3 papers, 2018 to 2024). "To date, only a few genes, such as those coding for peroxisome proliferator-activated receptors gamma (PPARγ), CCAAT-enhancer-binding proteins alpha (CEBPα), myogenin, myostatin, and matrix metallopeptidases (MMPs), have been identified in relation to muscle changes after rotator cuff tears." (PMID 30671462, 2018).
acute erythroid leukemia (2 papers, 2021 to 2024). An acute myeloid leukemia characterized by a predominant immature erythroid population. "The co-occurrence of GATA2 and CEBPa biallelic mutations is statistically significant in bi-lineage acute erythroid leukemia (AEL)." (PMID 34359655, 2021).
acute myelomonocytic leukemia (2 papers, 2021 to 2022). "Here, we report a case of acute myelomonocytic leukemia with a double mutation to the CCAAT/enhancer-binding protein alpha (CEBPA) gene during maintenance therapy for APL and include a review of the current literature." (PMID 33592885, 2021).
anemia (2 papers, 2017 to 2022). A reduction in the number of red blood cells, the amount of hemoglobin, and/or the volume of packed red blood cells. "Based on the direction of biological regulation mapping MYC, CEBPA, hsa-miR-29a, hsa-miR-29b, hsa-miR-29c and gene sets of extracellular domain could accurately display the occurrence mechanism of the side effect—anemia." (PMID 28729650, 2017). "For example, anemia related with the gene sets of extracellular region was regulated by hsa-miR-29a, hsa-miR-29b and hsa-miR-29c, and meanwhile MYC and CEBPA regulated the expression of these miRNAs." (PMID 28729650, 2017).
diabetic nephropathy (2 papers, 2023 to 2024). "In our study, we investigated the expression of CEBPA in patients with Diabetic Kidney Disease (DKD) using the Neproseq dataset." (PMID 39443466, 2024).
endometrial cancer (2 papers, 2008 to 2020). Primary or metastatic malignant neoplasm involving the endometrium (mucous membrane that lines the endometrial cavity). "DNA hypermethylation of the upstream CEBPA promoter region is responsible for very low CEBPA expression in lung and endometrial cancers." (PMID 32877461, 2020). "CEBPA expression is highly expressed in normal endometrial tissues and is not expressed in clinical endometrial cancer samples." (PMID 32877461, 2020).